DPP9 (dipeptidyl peptidase 9)
Diseases named in the same sentence as DPP9 in open-access papers (continued):
Sharing a sentence is not in itself a finding about the gene and the disease.
COVID-19 (continued). "This study reaffirmed previous findings that MUC5B, DPP9, and ATPase phospholipid transporting 11A (ATP11A) all represent shared genetic associations for both IPF risk and severity of COVID-19; however, crucially the analysis shows these findings are unified by a single causal variant." (PMID 37759460, 2023). "In conclusion, we have used genetic determinants of alternative splicing and COVID-19 outcomes obtained from large-scale studies and found compelling evidence that splicing events in OAS1, ATP11A, DPP9, NPNT, MUC1, and PMF1 have causal effects on COVID-19 severity and susceptibility." (PMID 37794074, 2023). "The expression level of DPP9 in COVID-19 male patients was higher than that in female patients, and the expression of DPP9 was correlated with gonadal steroids, suggesting that gender might be an important influencing factor." (PMID 36172198, 2022). "Furthermore, NLRP1-dependent pyroptosis is sufficient to cause progressive lung injury, independent of NLRP3 activation or IL-1b secretion, which suggests a relevant role of DPP9 in mediating lung injury seen in severe COVID-19." (PMID 34027315, 2021). "Thus, the aim of this study was to investigate the potential association between genic variants at rs1024611 (A>G), rs10774671 (A>G), and rs10406145 (G>C) of CCL2, OAS1, and DPP9 genes, respectively, and the severity of COVID-19 in a population from Quito, Ecuador." (PMID 38694517, 2024). "We could not completely exclude the potential of DPP9 as a gene associated with the severe COVID-19 phenotype due to undetectable genotype frequencies or small effects of these variants." (PMID 38694517, 2024). "Similarly, none of the alleles or genotypes of the DPP9 gene variant were significantly associated with the severe phenotype of COVID-19 according to the results of the multivariable logistic regression analysis." (PMID 38694517, 2024). "However, other loci as those in 3q12.3 (near RPL24) and 19p13.3 (near DPP9), previously found associated with COVID-19 severity, were not replicated in the SCOURGE Europeans." (PMID 35708486, 2022). "In critically ill patients with COVID-19, high levels of DPP9 may act to suppress inflammation." (PMID 36172198, 2022). "In addition to ABO blood type, receptors, and immune genes, GWAS studies on COVID-19 have revealed the association of SLC6A20 (rs2271616), LZTFL1 (rs10490770, rs11385942, rs73064425), and DPP9 (rs2109069) genes with respiratory failure caused by COVID-19 infection and critical illness." (PMID 36292769, 2022). "Furthermore, our DEG analysis of scRNA-seq of bronchoalveolar fluid of patients with COVID-19 showed that expression of DPP9, NLRP1, and GSDMD, an effector protein for pyroptosis, was significantly altered in Mo/Mφs of patients with severe COVID-19 compared to their moderate counterparts." (PMID 34027315, 2021). "Altogether, these findings support the relevance of ATP11A and DPP9 in IPF and COVID-19 pathogenesis." (PMID 39876559, 2025). "Upon the analysis of clinical characteristics among hospitalized COVID-19 patients, it was observed that rs17713054 SLC6A20-LZTFL1 (p = 0.006), rs12610495 DPP9 (p = 0.01), and rs17078346 SLC6A20-LZTFL1 (p = 0.01) were found to be linked with increased BMI." (PMID 39175753, 2024). "In the present study, we replicated associations of the rs17713054 SLC6A20-LZTFL1, rs17078346 SLC6A20-LZTFL1, rs12610495 DPP9 and rs7949972 ELF5 with severe COVID-19 within the Caucasian population of Central Russia." (PMID 39175753, 2024). "COLOC demonstrated moderately strong colocalization between the disease GWAS and IPF cases DPP9-eQTL signals (PP4 = 0.874 with IPF GWAS; 0.873 with COVID-19 GWAS) and weaker colocalization between the GWAS and control eQTL signals (PP4 = 0.661; 0.640)." (PMID 39040187, 2024). "In 23 lung COVID-19 autopsy donor tissue samples from GSE17166820, the expression of ATP11A, DPP9, MUC1, and NPNT were also enriched in alveolar type 1 and 2 epithelial cells." (PMID 37794074, 2023).
COVID-19 (continued). "Last, we show that ATP11A, DPP9, NPNT, and MUC1 are highly expressed in lung alveolar epithelial cells, both in COVID-19 uninfected and infected samples." (PMID 37794074, 2023). "Colocalization analyses support a shared genetic mechanism between COVID-19 severity with idiopathic pulmonary fibrosis at the ATP11A and DPP9 loci, and with chronic obstructive lung diseases at the NPNT locus." (PMID 37794074, 2023). "IPF32 and critical illness due to COVID-19 were highly colocalized at the ATP11A and DPP9 sQTL loci with a posterior probability of 1.00." (PMID 37794074, 2023). "However, the possible role of DPP9 in COVID-19 remains unclear." (PMID 36172198, 2022). "We suspect that lower DPP9 may exacerbate pathogenesis of IPF and COVID-19 by preventing excess NLRP1-mediated inflammation and weakening cell-to-cell adhesion, promoting a dysregulated cycle of inflammation and fibrosis." (PMID 39876559, 2025). "However, for treatment of COVID-19 and IPF, increasing DPP9 expression or activity seems to be the desired outcome." (PMID 39876559, 2025). "We hypothesized that DPP9 would be decreased during IPF and COVID-19 in fibroblasts and other cell types that increase in proportion during IPF based on our GWAS and eQTL colocalization in fibroblasts and IPF lung." (PMID 39040187, 2024). "We identify that alternative splicing in lung, rather than total expression of OAS1, ATP11A, DPP9 and NPNT, is associated with COVID-19 severity." (PMID 37794074, 2023). "Interestingly, the available evidence suggests shared genetic mechanisms for COVID-19 severity with IPF at the ATP11A and DPP9 loci, and with chronic obstructive lung diseases at the NPNT locus." (PMID 37794074, 2023). "We did not observe significant differences in MUC5B or DPP9 expression in lungs from patients who died of COVID-19 when compared with control lungs, which could be due to the limited number of samples in the study we examined (GEO: GSE159585)." (PMID 39876559, 2025). "We did not observe significant differences in MUC5B or DPP9 expression in lungs from patients who succumbed to COVID-19 when compared to control lungs, which could be due to the limited number of samples in the study we examined (GSE159585)." (PMID 39040187, 2024). "Taken together, these expression evidence suggests that the transcriptional splicing—COVID-19 outcome relationships for ATP11A, DPP9, MUC1, and NPNT were likely to be relevant in lung tissue and these signals may be especially important in alveolar epithelial cells." (PMID 37794074, 2023).
pulmonary fibrosis (12 papers, 2020 to 2026). Chronic progressive interstitial lung disorder characterized by the replacement of the lung tissue by connective tissue, leading to progressive dyspnea, respiratory failure, or right heart failure. "We use colocalization and transcriptomic analyses to identify shared genetic variants, likely causal genes including ATP11A and DPP9, and important cellular contexts for critically ill COVID-19 and idiopathic pulmonary fibrosis." (PMID 39876559, 2025). "For the causal genes with new evidence presented here, DPP9 may be particularly attractive, and inhibitors in development have been speculated to be therapeutic for pulmonary fibrosis." (PMID 39876559, 2025). "Furthermore, the DPP9 gene was linked to idiopathic pulmonary fibrosis by genome-wide association studies (GWAS)." (PMID 36172198, 2022). "Genome-wide association studies (GWAS) have found several risk loci mapping to the DPP9 gene on chromosome 19 (19p13.3) that contribute to human diseases, including alcoholism, interstitial lung abnormalities, pulmonary fibrosis and adolescent idiopathic scoliosis." (PMID 33915844, 2021). "The two important DPP9 intronic variants (rs12610495 and rs2109069) were found to be associated with pulmonary fibrosis and severe COVID but not with liver cancer." (PMID 33915844, 2021).
acute myeloid leukemia (8 papers, 2013 to 2025). Acute myeloid leukemia (AML) is a group of neoplasms arising from precursor cells committed to the myeloid cell-line differentiation. "Using Val-boroPro, 1G244 and some isoindoline derivatives to inhibit DPP9 induces significant cell death in many human acute myeloid leukemia (AML) cell lines, suggesting a therapeutic potential of DPP9-selective inhibition in AML." (PMID 40293537, 2025). "Consistently, VBP and the more selective DPP8/DPP9 inhibitor 1G244 were shown to engage the inflammasome adaptor protein CARD8 to induce pyroptosis of a panel of acute myeloid leukemia (AML) cell lines and primary AML samples." (PMID 30718379, 2019). "Furthermore, Val-boroPro suppresses human acute myeloid leukemia (AML) growth in mouse models by triggering pyroptosis in AML cells via DPP9 inhibition." (PMID 34771657, 2021). "The DPP family nonselective inhibitor Val-boroPro (talabostat) triggers a lytic form of programmed cell death known as pyroptosis in human acute myeloid leukemia (AML) cell lines and primary AML samples, an effect that is dependent on DPP9 inhibition." (PMID 37048172, 2023). "DPP8 and DPP9 can regulate pyroptosis in human acute myeloid leukemia, while DPP8 and DPP9 mRNAs are overexpressed in ovarian carcinoma." (PMID 34359286, 2021). "The potential importance of DPP9 in tumor biology has also been shown by inhibition of DPP9 and DPP8 enhancing parthenolide's anti-leukemic activity in primary acute myeloid leukemia samples and lymphoma and leukemia cell lines." (PMID 24223149, 2013). "Small-molecule inhibitors of the serine dipeptidases DPP8 and DPP9 (DPP8/9) activated CARD8 and caspase-1 to trigger pyroptosis in the majority of human acute myeloid leukemia (AML), indicating the protein CARD8 could be a novel therapeutic target for AML." (PMID 34298833, 2021).
breast carcinoma (6 papers, 2021 to 2025). "High DPP9 expression in patients with breast cancer associates with longer survival time, while low DPP9 expression is associated with poorer survival of these patients." (PMID 40293537, 2025). "For example, previous studies reported associations of DPP9 expression with patient survival in non–small-cell lung cancer, breast cancer, colorectal cancer, and oral squamous cell carcinoma." (PMID 40355159, 2025). "Previous bioinformatics revealed the upregulated DPP9 expression in breast cancer was associated good prognosis." (PMID 35685372, 2022). "These outcomes occur in patients with luminal A subtype, the most common breast cancer subtype, which has the greatest DPP9 gene expression levels." (PMID 40293537, 2025). "For example, DPP9 activity is important for fine-tuning the levels of BRCA2 a prominent tumour suppressor in breast cancer and thus for ensuring correct repair of DNA DSBs by homologous recombination." (PMID 40293537, 2025). "In our study, we investigated the impact of DPP8 and DPP9 on breast cancer cells representing different molecular subtypes." (PMID 37626841, 2023). "In breast cancer, DPP9 expression was elevated, and high DPP8/9 expression correlates with a good prognosis." (PMID 36172198, 2022). "A report in 2022 has shown that breast cancer-associated protein 2 (BRCA2), a substrate of DPP9, plays an essential role in a variety of tumors, including HCC and breast cancer." (PMID 36172198, 2022). "High expression levels of DPP3 and DPP4 were associated with poor survival of breast cancer patients, whereas high expression levels of DPP6, DPP7, DPP8, and DPP9 were associated with good prognoses." (PMID 34359286, 2021). "DPP3 and DPP9 mRNA expression levels were upregulated in breast cancer tissues relative to normal breast tissues and other subtypes." (PMID 34359286, 2021). "The results showed that DPP3 and DPP9 had significantly high expression profiles in breast cancer tissues relative to normal breast tissues." (PMID 34359286, 2021). "Furthermore, DPP9 depletion in a breast cancer mouse model delays tumour onset but ultimately promotes metastasis, by increased levels of the zinc finger transcription factor ZEB1 and accelerated TGF-β1 induced epithelial-to-mesenchymal transition (EMT)." (PMID 40293537, 2025). "Overall, a full understanding for the influence of DPP9 is less clear in breast cancer." (PMID 40293537, 2025). "In summary, both DPP8 and DPP9 activities confine macroautophagy in breast cancer cells." (PMID 37626841, 2023). "And DPP9 was found to be involved in the metastasis of breast cancer cells." (PMID 36172198, 2022). "Notably, DPP9 prefers to regulate the cell behaviour through EGFR signalling which is a dominant signalling in the TNBC subtype of breast cancer, DPP9 tends to be a pivotal molecule in TNBC." (PMID 35685372, 2022). "Although DPP8 and DPP9 have been shown to influence tumor growth in various entities, like Ewing sarcoma, cervical cancer, or non-small-cell lung cancer, their role in breast cancer is unknown." (PMID 37626841, 2023). "Results from an Oncomine analysis showed that mRNA expression levels of DPP3 and DPP9 were highly upregulated in breast cancer tissues, whereas DPP4, DPP6, and DPP8 exhibited downregulated levels in breast cancer tissues relative to normal breast tissues." (PMID 34359286, 2021). "It suggests that upregulated DPP9, LRRC20 and TTBK2 together with downregulated TTC17, ZNF75D and CYTH2 may play pivotal role in the orchestrated adaptive homing of metastatic breast cancer cells in bone niche." (PMID 35685372, 2022). "Our data showed that DPP8 had low expression levels in breast cancer tissues at both the transcription and protein levels whereas DPP9 did not, and both of them were related to good prognoses in breast cancer patients." (PMID 34359286, 2021).
breast carcinoma (continued). "Data demonstrated that DPP3, DPP7, DPP8, DPP9, and DPP10 mostly had medium protein expression levels, while some clinical tissues showed strong positive expression levels of DPP3, DPP7, and DPP9 in breast cancer specimens." (PMID 34359286, 2021). "GDF11, CD151, PAFAH1B2 and YTHDF2 may play a pivotal role in the predisposition of metastasis to the bone from breast cancer, whilst DPP9, FAS, ZNF519, RPP14 and FAU may be actively involved in the adaptative colonisation of metastatic breast cancer cells in bone." (PMID 35685372, 2022). "This family comprises seven members, including DPP3, DPP4, DPP6, DPP7, DPP8, DPP9, and DPP10; however, information on the involvement of DPPs in breast cancer is lacking in the literature." (PMID 34359286, 2021).
non-small cell lung carcinoma (6 papers, 2018 to 2026). A group of at least three distinct histological types of lung cancer, including non-small cell squamous cell carcinoma, adenocarcinoma, and large cell carcinoma. "In contrast, DPP9 deficiency in non-small-cell lung cancer cells, as well as DPP8 deficiency in cervical cancer cells, reduced proliferation." (PMID 37626841, 2023). "Previous studies reported associations of DPP9 expression with patient survival in non-small-cell lung cancer, colorectal cancer and oral squamous cell carcinoma." (PMID 33915844, 2021). "In a study of non-small cell lung cancer, it was found that inhibition of DPP9 expression in A549 and H1299 cell lines reduced cell migration and invasion." (PMID 36172198, 2022). "Overexpression of DPP9 correlates with poor 5-year overall survival in patients with non-small cell lung cancer." (PMID 30487758, 2018). "A study using a non-small-cell-lung cancer (NSCLC) model demonstrated that knockdown of DPP9 could inhibit lung cancer cell proliferation, migration and tumorigenesis." (PMID 33915844, 2021).
ovarian carcinoma (6 papers, 2013 to 2025). A malignant neoplasm originating from the surface ovarian epithelium. "We observed that DPP8 and DPP9 LoF variants were more commonly diagnosed with a gynecological cancer, such as UCEC, cervical cancer or ovarian cancer." (PMID 33915844, 2021). "Dipeptidyl peptidase 9 (DPP9) is a member of the S9b protease family and DPP9 mRNA expression is associated with longer survival for patients with uterine corpus endometrial carcinoma and ovarian cancer." (PMID 35054873, 2022).
clear cell renal carcinoma (5 papers, 2024 to 2025). A malignant epithelial neoplasm of the kidney characterized by the presence of lipid-containing clear cells within a vascular network. "Upregulation of dipeptidyl peptidase 9 (DPP9) increases the stabilization of NRF2, thus boosting sorafenib resistance in clear cell renal cell carcinoma cells." (PMID 39624080, 2024). "Unlike our findings, they found that DPP9 inhibited ferroptosis and induced sorafenib resistance in Clear Cell Renal Cell Carcinoma not by regulating the NRF2 downstream target gene NQO1, but by regulating SLC7A11." (PMID 39094401, 2024). "Similarly, DPP9 disrupts KEAP1‐NRF2 binding through its conserved ESGE motif, leading to NRF2‐dependent transcriptional activation of SLC7A11 and promoting tumorigenesis and drug resistance in renal clear cell carcinoma." (PMID 40583858, 2025). "Furthermore, dipeptidyl peptidase 9 (DPP9) competes with NRF2 for binding to KEAP1 in an enzyme-independent manner, thereby disrupting the KEAP1-NRF2 signaling pathway and influencing tumorigenesis and drug resistance in clear cell renal carcinoma (ccRCC)." (PMID 39544949, 2024).